FLI1 (Fli-1 proto-oncogene, ETS transcription factor)
Diseases named in the same sentence as FLI1 in open-access papers (continued):
Sharing a sentence is not in itself a finding about the gene and the disease.
tumor (continued). "ets21c encodes the single ortholog of human Friend leukemia insertion 1 (FLI1) and ETS-related gene (ERG) that are commonly overexpressed or translocated in various tumor types." (PMID 26398940, 2015). "The tumor cells show diffuse strong expression of Factor VIII, Fli-1, INI-1, vimentin, MDM2, and CDK4, local expression of CD31, AE1/AE3, EMA and P63, and no expression of CD34, S-100, actin-sm, desmin, MyoD1, and HMB45." (PMID 26315812, 2015). "Immunohistochemistry showed that the tumor cells were strongly positive for BCL-2, CD 99, Vimentin, FLI1 and neuron-specific enolase (NSE)." (PMID 24715974, 2014). "The patients’ RNA from tumor and normal peritumoral tissue was extracted and EWS/FLI-1 fusion screened by quantitative real-time PCR." (PMID 25870707, 2014). "The tumor showed diffuse and strong positivity for CD31, CD34, FLI1, and INI1, with smooth muscle actin (SMA) positive surrounding smooth muscle layers around most vessels." (PMID 24383023, 2013). "Another study using mice showed decreased tumor size and levels of EWS/FLI-1 after the use of an antisense ODN nanocapsules." (PMID 22523703, 2012). "Classical ES and PNET possessing variable degrees of differentiation are now known to be the same tumor type, defined by a translocation between the EWS gene on chromosome 22 with one of three ETS-like genes, especially the Fli1 gene on chromosome 11." (PMID 29147265, 2011). "All specimens showed either an EWS/FLI1 or an EWS/ERG transcript by RT-PCR, indicating at least some ESFT tumor cell content." (PMID 19859563, 2009). "The biology of these aggressive malignancies centers around EWS/FLI1 and related EWS/ETS chimeric transcription factors, which are largely limited to this tumor class." (PMID 19859563, 2009). "The faster tumour growth rate of this clone HuEF#16 was consistent with its more rapid growth rate observed in vitro and higher expression of EWS/FLI-1." (PMID 12556973, 2003). "To determine the ability of the KRAB/FLI-1 repressor to influence tumour development of SK-N-MC cells, we inoculated clones of SK-N-MC cells expressing KRAB/FLI-1 or mutant KRAB/FLI-1 and control cells into nude mice." (PMID 12556973, 2003). "In contrast, RT-PCR revealed the presence of chimaeric transcripts in 28 tumours (93%), with fusions of EWS exon 7 to FLI-1 exons 6 (19/28), 5 (4/28) and 7 (1/28)." (PMID 7524604, 1994). "The tumor cells may be arranged in Homer-Wright rosettes, and IHC often shows strong positivity for CD99 and FLI-1." (PMID 41230381, 2026). "Consistent with the results in cultured cells, the ability of ITZ to suppress TC-71 xenograft growth was counteracted by ectopic expression of EWSR1::FLI1, indicating that the reduced levels of EWSR1::FLI1 following ITZ treatment were responsible for the reduction in tumor growth." (PMID 39894896, 2025). "Importantly, the authors also demonstrated that tumour-related genes, such as NNMT, FLI1, GAS6, lncRNA CCAT1, PDCD1LG2, and CD274, were key regulators of neoplastic transformation in response to a low multiplicity of oral pathogen infection." (PMID 41228271, 2025). "Histopathological examination of the epididymal biopsy showed tumor cells with specific morphological features, and immunohistochemistry (IHC) indicated CD31(+), CD34(+), Fli-1(+), ERG(+), Ki-67(+5%+), along with WWTR1-CAMTA1 gene fusion by fluorescence in situ hybridization (FISH), confirming EHE." (PMID 40978723, 2025). "Therefore, immunohistochemistry (IHC) is necessary to confirm the tumor’s endothelial origin, with markers like CD31, CD34, FLI1, and ERG being particularly useful for identifying vascular differentiation." (PMID 40004808, 2025).
tumor (continued). "Moreover, our investigation reveals a significant downregulation in the expression levels of these uEV-associated biomarkers after surgery, indicating the likely secretion of SRGN, FLI1, and MACROH2A2 by tumor cellular EVs." (PMID 39816677, 2025). "Considering the tumor purity of TGCA samples, we also performed the purity correction before correlation analysis, and the results revealed that FLI1 was also positively correlated with these three checkpoint molecules in BRCA in both the TGCA and TIMER databases." (PMID 38448802, 2024). "Chemical composition analysis identified other compounds previously known having anti-tumor activity independent of the FLI1 blockade." (PMID 39769192, 2024). "Moreover, overexpression of FLI1 in K562 (K562-fli1) cells resulted in downregulation of HSPA1B suggesting a tumor suppressor role for this gene." (PMID 38461240, 2024). "Intriguingly, we find that pharmacological inhibition of FLI1 effectively obstructs the CBP/STAT1-IDO1-Kyn axis, thereby invigorating both spontaneous and checkpoint therapy-induced immune responses, culminating in enhanced tumor eradication." (PMID 38816360, 2024). "SCRIPro could accurately predicts well-known master regulators including SPI1, IRF1, FLI1, and STAT2 for mono/macrophages, GATA3, RUNX3, SMARCA4, JUND, and MYB for T-cells, PAX5, BCL2, and IRF4 for B and tumor B-cells." (PMID 39024032, 2024). "However, the core genes that drive the enrichment score in the gene set regulated by CD99 are different from those dependent on EWS::FLI1, supporting a functional complementarity between EWS::FLI1 and CD99 in the regulation of tumor malignancy." (PMID 39524141, 2024). "BARD1 as a putative tumor suppressor, interacts with the N-terminus of EWSR1::FLI1." (PMID 36672331, 2023). "Immunohistochemically, tumor cells were positive for AE1/AE3, CD31, FLI-1 and ERG." (PMID 34514569, 2022). "Using the Tg(fli1:EGFP) zebrafish strain, which expresses enhanced green fluorescent protein (EGFP) throughout the vasculature, we followed the effects of 5-Aza on tumor angiogenesis." (PMID 35406401, 2022). "With a xenograft tumor model, the anti-growth role of circ-FLI1 silencing was also found in vivo with or without L-OHP treatment." (PMID 35647294, 2022). "The coregulatory role of FLI1 in promoting HIF‐1‐mediated angiogenesis and glucose utilization identified in the present study may therefore provide new mechanistic insights into tumor growth and progression to malignancy." (PMID 34102031, 2021). "IHC studies show the tumor cells to be positive for FLI-1 and negative for S100 protein, SOX10, desmin, myogenin, WT1, SMA, CD34 and pan-cytokeratin." (PMID 34745213, 2021). "It is an aggressive tumor, genetically characterized by epigenetic remodeling induced by a fusion gene involving the EWS gene and an ETS transcription factor gene, most commonly (> 95%) the FLI1 or ERG genes." (PMID 32115849, 2020). "The correlation between module eigengenes and FLI1 expression level, PD‐1 expression level, PD‐L1 expression level, CTLA expression level, CYT, tumour purity, ESTIMATE score, immune score, leucocyte fraction, TIL regional fraction and LI signature score of BRCA patients were identified." (PMID 32249526, 2020). "The BRCA samples with FLI1 expression level, PD‐1 expression level, PD‐L1 expression level, CTLA expression level, CYT, tumour purity, ESTIMATE score, immune score, leucocyte fraction, TIL regional fraction and LI signature score were included in co‐expression analysis." (PMID 32249526, 2020). "The tumor cells were strongly and diffusely positive for AE1/AE3, FLi-1, ERG and FOSB." (PMID 31311568, 2019). "To examine whether 419S1 and 420S1 can block tumor cell migration and proliferation, we injected 293T/EDN1 cells labelled with CM-Dil (red fluorescence) into 2 dpf embryonic yolk sacs of Tg(fli1:EGFP)." (PMID 31141996, 2019).
tumor (continued). "Furthermore, in CHP100 (the type 2 fusion of EWS/FLI1) which had a low XBP1 expression, toyocamycin exerted significant anti-tumor activities and also activated apoptosis." (PMID 29581854, 2018). "Except for few being chromatin regulators (CGBP, MBD2, and DNMT1), all of these TFs were found to have tumor suppressor functionality (BRCA1, E2F1&2&5&7, EGR1-4, FLI1, NRF1, TFDP2, and STAT1), or indirectly mediate the suppression of tumorigenesis and tumor suppressor activity (SP4 and ZBTB33)." (PMID 29740534, 2018). "Taken together, NNMT, FLI1, GAS6, lncRNA CCAT1, PDCD1LG2, and CD274, whose differential expression was confirmed, may be involved in the major mechanism of tumor-like transformation induced by chronic P. gingivalis infection." (PMID 28286742, 2017). "We have shown that the Ews-Fli1 reciprocal translocation event did not induce tumor formation when expressed in mouse tissues using specific Cre strains." (PMID 27191748, 2017). "In future studies, we will be focusing on whether FLI1 indeed regulates the transcription of CCAT1 and how FL11-regulated CCAT1 functions on tumor-like transformation of HIOECs induced by P. gingivalis." (PMID 28286742, 2017). "As expected, restoring the expression of FLI-1 in OS cells abolished miR-145-mediated suppression, suggesting that FLI-1 might have a key role in miR-145 mediated OS tumor suppression." (PMID 27304058, 2016). "EWS/FLI1 suppresses miRNAs such as let-7a, which normally suppresses transcriptional targets of STAT3, MMP-2 and CCND-2, leading to increased macrophage infiltration, tumor proliferation, and metastasis." (PMID 28536380, 2016). "Immunohistochemically, the tumor cells showed diffuse membrane positivity for CD99, Syn and FLI1." (PMID 25780425, 2015). "In our patient, the tumor cells also stained positive for NSE and FLI1." (PMID 24715974, 2014). "FOXM1 expression is enhanced by EWS/FLI1, though, unlike other tumor systems, it is not driven by expression of the EWS/FLI1 target GLI1." (PMID 23365673, 2013). "In all 50% of the mice inoculated with clones expressing both KRAB/FLI-1 and EWS/FLI-1 did develop small palpable tumours (7±2 mm3) in the latter part of the experiment; however, these tumours continued to grow very slowly (data not shown)." (PMID 12556973, 2003). "For example, at day 15 100% of mice had developed tumours in the parental and mutant KRAB/FLI-1-expressing cells (mean tumour volume 113±23 and 111±22 mm3, respectively), whereas only 50% of mice inoculated with KRAB/FLI-1-expressing cells had palpable tumours (mean volume 34±8 mm3)." (PMID 12556973, 2003). "For example, mouse Ews/Fli-1-transformed cells coexpressing mutant KRAB/FLI-1 formed tumours in nine out of 10 mice inoculated with a mean size of 96±26 mm3 by day 30; however, at the same stage no tumours were observed in cells coexpressing KRAB/FLI-1." (PMID 12556973, 2003). "Additionally, we found an apparent trend that, regardless of cell type, the expression of FLI1 was largely augmented in tumor-involved axillary lymph node samples compared with normal breast tissues and BRCA tissues except mesenchymal cells." (PMID 38448802, 2024). "In some cases, tumor cells may also test positive for NSE and FLI1." (PMID 37170363, 2023). "The tumor was found to be positive for cluster of differentiation (CD) 99, vimentin, and Friend leukemia integration 1 transcription factor (FLI1), and negative for leukocyte common antigen (LCA) and synaptophysin with a 7% Ki 67 positivity confirming the diagnosis of EES." (PMID 36465784, 2022).
tumor (continued). "Instead, MRD detection in these cancers has focussed on the detection of tumour-specific messenger RNA (mRNA) using qRT-PCR of NB-specific RNA markers, such as TH and PHOX2B, or EWSR1 gene fusion transcripts with the ETS family or FLI1 gene for EWS-specific markers." (PMID 34471258, 2022). "Given this problem, it seems prudent to consider the combination of inhibitors against EWSR1/FLI1 or EWSR1/ERG with additional targeted therapies that might overcome tumor cells’ resistance to the monotherapy and might demonstrate a less adverse effect due to dose reduction." (PMID 35454895, 2022). "As new findings emerge about the contribution of tumor cell heterogeneity to tumor progression, drug resistance, and metastasis, a deeper understanding of the features that regulate EWS::FLI1 activity may inform the development of targeted therapies that can moderate them." (PMID 36505823, 2022). "It is an aggressive tumor typically characterized by a fusion of the Ewing sarcoma breakpoint region 1 (EWSR1) with an erythroblast transformation specific (ETS) transcription factor gene, most frequently (>95%) the friend leukemia virus integration 1 (FLI1) gene." (PMID 34359637, 2021). "Moreover, EwS tumors have well-established genetic aberrations that can be used for comparison, most notably the tumor-defining chromosomal translocation between EWSR1 and an Ets family member gene (most commonly FLI1), and a small number of recurrent CNAs46–48." (PMID 34050156, 2021). "Several studies have shown that Friend leukemia virus integration 1 (Fli-1), a transcription factor in the E26 transformation-specific factor (ETS) family, plays an important regulatory role in the generation of vascular endothelial cells and proliferation of tumor cells." (PMID 32210104, 2020). "Furthermore, fucoidan interrupted tumor and vascular formation in zebrafish xenograft and fli1 Tg model, respectively, whereas it did not exhibit toxicity in normal zebrafish." (PMID 31936539, 2020). "Because the vessels of the Tg (fli1: EGFP) zebrafish could glow with a green fluorescence, we found that the number of new formed twisty tumour vessels in the zebrafish injected with 231-lenti-ACE2 cells was less than that found in the zebrafish injected with 231-lenti-Vec cells." (PMID 31023337, 2019). "In combining results of bioinformatics analyses and validation assays, tumor-related genes such as NNMT, FLI1, GAS6, lncRNA CCAT1, PDCD1LG2, and CD274 may be considered as the key regulators in tumor-like transformation in response to long-time exposure of P. gingivalis." (PMID 28286742, 2017). "Many researchers in the field could not detect expression of FLI1-EWS mRNA or protein in ES cell lines or human tumor samples." (PMID 27191748, 2017). "Also, Tg (fli1:EGFP)y1 fish stably expressing EGFP in all blood vessels throughout embryogenesis clearly, were utilized to demonstrate interactions between metastatic tumor cells and host vessels." (PMID 23613942, 2013). "However, attempts to express EWS/FLI-1 in mice or murine mesenchymal cells have resulted in the development of leukemia, not sarcoma, and no tumor formation whatsoever." (PMID 22523703, 2012). "However, when triple-negative PDX cells were injected in zebrafish embryos Tg (Fli1: eGFP) and subsequently treated with HS-binding peptide, the tumor size decreased, and there was also an increase in the survival rate of the zebrafish embryos, suggesting an antitumor efficacy of HS-binding peptide." (PMID 34422650, 2021). "Furthermore, “endpoint” PCR to detect the transposon insertion in Fli1 in this tumor only generated a product with the highest amounts of input tumor genomic DNA tested, also indicating that the insertion is not highly clonal within the tumor." (PMID 25423036, 2014).
tumor (continued). "Similarly, in mice inoculated with human EWS/FLI-1 clone #16 coexpressing KRAB/FLI-1, no tumours were observed at day 27; however, tumours formed in nine out of 10 mice inoculated with the same clone expressing mutant KRAB/FLI-1 with a mean volume of 147±32 mm3." (PMID 12556973, 2003). "The tumor was positive for CD99, SATB2, TLE1, cyclin D1, and focal FLI1, while negative for EMA, S100, desmin, calponin, and SOX10." (PMID 41869091, 2026). "The transcriptomic dynamics of cells with or without expression of EWS::FLI1 or CD99 were analyzed and correlated with tumor cell growth." (PMID 39524141, 2024). "Histologically, a cellular tumor comprising malignant oval to spindle cells with necrosis was observed, which was positive for Bcl-2, CD99, and FLI-1, but negative for pan-cytokeratin, STAT6, and CD34." (PMID 36033527, 2022). "Tumor cells were negative for, CD34, CD31, v-ets erythroblastosis virus E26 oncogene like isoform 2 (ERG), and FLI1." (PMID 35615157, 2022). "As expected, tumor cells had nuclear localization of EWSR1-FLI1, whereas control fish had no expression of FLI1 in the corresponding sites." (PMID 35285802, 2022). "Immunohistochemically, the tumor cells are positive for CD31, ERG, FLI1, and cytokeratin (AE1/AE3), but negative for CD34." (PMID 32316685, 2020). "Immunohistochemically, the tumor cells were diffusely positive for CD34, STAT-6 and FLI-1, but negative for pan-cytokeratin, CAM5.2, p63, S100 protein, CD31, SMA, and calponin." (PMID 30777087, 2019). "Depletion of USP19 was shown to decrease EWSR1-FLI1 expression levels, but neither the expression of wild-type of EWSR1 nor FLI1, and to reduce tumor growth in vitro and in vivo indicating a potential therapeutic value for USP19 inhibition." (PMID 31970591, 2019). "The tumor cells were positive for CD99, FLI1 and EMA, but negative for CD3, CgA, CD20, CKpan, S100 and HMB45." (PMID 25780425, 2015). "Besides, relative DKC1 mRNA expression was increased in CC patients’ tumors, and tumor tissue DKC1 mRNA expression was with negative correlation with miR-197-3p and positive correlation with circ-FLI1." (PMID 35647294, 2022). "While FLI1 acts as an oncogene, the ability of this TF to induce WASP/WIP, which has a negative growth promoting activity, may counteract its tumor promoting activity." (PMID 33717090, 2021). "However, the tumor cells were negative for S-100 protein, SMA, desmin, myogenin, CD99, Fli-1, CD56, STAT6, CK and EMA." (PMID 32957984, 2020). "The tumor cells were diffusely positive for CD34, STAT-6 and FLI-1, and negative for pan-cytokeratin, CAM5.2, p63, S100 protein, CD31, SMA, and calponin.ERG and Ki67 immunostaining showed an accentuated nuclear staining pattern in the central dedifferentiated area." (PMID 30777087, 2019). "In our case, the tumor cells expressed CD31, AE1/AE3, FLi-1, and ERG and were negative for CD34." (PMID 31311568, 2019). "By normalizing to a line that did not express mouse Ews-Fli1 and using a positive control for mouse Ews-Fli1 expression (mouse EWS-FLI1-overexpressing MEFs), we demonstrated that none of the tumors from the Ink4a/Arf tumor study expressed Ews-Fli1 at levels above background." (PMID 27191748, 2017).